LCMT1 (leucine carboxyl methyltransferase 1)
Description:
Methylates the carboxyl group of the C-terminal leucine residue of protein phosphatase 2A catalytic subunits to form alpha-leucine ester residues.
Synonyms: LCMT; CGI-68; PPMT1
Tractability: Small molecule: a structure with a bound ligand is known; it has a high-quality binding pocket. PROTAC: ubiquitination databases record sites on it; its protein half-life has been measured.
Gene: Protein-coding gene on chromosome 16 (25,111,731 to 25,178,231, forward strand). Ensembl gene ENSG00000205629.
Subcellular location (Human Protein Atlas): Cytosol; Nucleoplasm
Pathways (Reactome):
Cell Cycle: Cyclin A/B1/B2 associated events during G2/M transition
Gene Ontology:
Molecular function: protein binding; protein C-terminal carboxyl O-methyltransferase activity; protein C-terminal leucine carboxyl O-methyltransferase activity; S-adenosylmethionine-dependent methyltransferase activity; methyltransferase activity
Biological process: C-terminal protein methylation; negative regulation of protein-containing complex assembly; protein methylation; regulation of apoptotic process; regulation of mitotic cell cycle spindle assembly checkpoint; G2/M transition of mitotic cell cycle; protein modification process; regulation of signal transduction
Cellular component: cytosol; nucleoplasm
Genetic constraint (gnomAD): Loss-of-function variants: 17 observed, 26.66 expected, observed/expected ratio (o/e) 0.64, 90% interval 0.44 to 0.96. The upper end of that interval is the gene's LOEUF score, 0.96, which puts it in group 4 of 6, group 1 being the genes least tolerant of losing a copy. Missense variants: 259 observed, 285.81 expected, observed/expected ratio (o/e) 0.91, 90% interval 0.82 to 1. Synonymous variants: 105 observed, 107.92 expected, observed/expected ratio (o/e) 0.97, 90% interval 0.83 to 1.14.
Homologues: Orthologues: chimpanzee LCMT1 (100% identical), macaque LCMT1 (97% identical), dog LCMT1 (89% identical), mouse Lcmt1 (88% identical), guinea pig LCMT1 (84% identical), rat Lcmt1 (81% identical), rabbit LCMT1 (79% identical), tropical clawed frog lcmt1 (67% identical), zebrafish lcmt1 (63% identical), Drosophila melanogaster CG3793 (47% identical), Caenorhabditis elegans lcmt-1 (37% identical). Paralogues in human: LCMT2 (35% identical).
Diseases named in the same sentence as LCMT1 in open-access papers:
LCMT1 is named in the same sentence as 22 diseases in open-access papers, as found by Europe PMC text mining. Sharing a sentence is not in itself a finding about the gene and the disease. The quoted sentences say what the papers report.
Cognitive impairment (4 papers, 2022 to 2025). Abnormal cognition is characterized by deficits in thinking, reasoning, or remembering. "Our data strongly support that chronic hypoxia promotes HIF-1α expression, leading to LCMT1/PP2Ac deficiency and tau hyperphosphorylation, finally resulting in cognitive impairments." (PMID 36555780, 2022). "A contextual fear conditioning task was used as an additional test of the ability of LCMT‐1 overexpression to protect against tau‐induced cognitive impairments." (PMID 41388803, 2025). "This leads to a decrease in LCMT1 protein level which in turn decreases PP2Ac methylation and thus activity, finally resulting in tau hyperphosphorylation and cognitive impairment." (PMID 36555780, 2022). "In the current study, we provide extensive evidence demonstrating chronic hypoxia upregulating HIF-1α, decreasing the level of LCMT1, leading to PP2A deficiency, and resulting in tau hyperphosphorylation and cognitive impairments." (PMID 36555780, 2022). "Since our behavioral data suggest that LCMT‐1 overexpression protects against tau‐induced cognitive impairments, we sought to determine whether LCMT‐1 overexpression might also protect against the tau‐induced impairments in synaptic plasticity." (PMID 41388803, 2025). "The effects of LCMT‐1 and PME‐1 overexpression on cognitive impairments produced by oligomeric tau from shockwave‐exposed mice were not accompanied by impairments in visible platform water maze performance, shock perception, or open field behavior." (PMID 41388803, 2025). "Our further study showed that conversely, HIF-1α silencing recovered chronic hypoxia-induced LCMT1/PP2Ac/tau axis alterations and attenuated cognitive impairment, strongly supporting that HIF-1α downregulates the LCMT1/PP2Ac axis to induce tau pathology." (PMID 36555780, 2022). "Together, our data strongly support the notion that HIF-1α regulates LCMT1 and lowers PP2A activity, mediating tau phosphorylation and cognitive impairments in chronic hypoxia." (PMID 36555780, 2022).
prostate carcinoma (4 papers, 2022 to 2025). A carcinoma that arises from epithelial cells of the prostate gland. "Together, these data demonstrate that the loss of methylation-sensitive PP2A heterotrimers from the chromatin upon LCMT1 silencing results in hyperphosphorylation mediated amplified AR-signaling leading to ligand-independent AR addiction, a hallmark of prostate cancer." (PMID 37644036, 2023). "LCMT1 methylates the C-terminal leucine of PPP2R2A to regulate PP2A substrate specificity and has been implicated in prostate cancer through AR regulation." (PMID 40493189, 2025). "Here, we report that the leucine carboxy methyltransferase (LCMT1), which methylates the L309 residue of the C subunit, acts as a suppressor of androgen receptor (AR) addicted prostate cancer (PCa)." (PMID 37644036, 2023). "Together, these data suggest Pten deletion and PI3K-AKT activation drive prostate cancer initiation and progression through degradation of LCMT1 and biased PP2A heterotrimer formation." (PMID 37644036, 2023). "To investigate the phosphorylation status of AR and MED1 as a consequence of methyl-PP2A-C loss and the resultant bias in PP2A heterotrimer formation upon LCMT1 silencing, we employed a panel of prostate cancer cell lines stably expressing shRNA to LCMT1." (PMID 37644036, 2023). "Silencing LCMT1 increases AR activity and promotes castration-resistant prostate cancer growth." (PMID 37644036, 2023). "In addition, we identified S6K1/β-TRCP mediated degradation of LCMT1 as a mechanism for the restoration of AR signaling in antiandrogen refractory prostate cancer cells." (PMID 37644036, 2023). "Analysis of the TCGA prostate dataset revealed no significant change in the expression of LCMT1 mRNA or any mutation in its coding sequence or genomic deletion in primary prostate cancer and benign prostate tissue." (PMID 37644036, 2023). "Here, the authors show that decreased methylation of PP2A catalytic C subunit caused by loss of LCMT-1 in prostate cancer abrogates the tumor suppressor activity of PP2A on AR/MED1-dependent gene expression, proposing decreased methyl-PP2A-C as a prognostic marker for prostate cancer progression." (PMID 37644036, 2023). "Together, these results demonstrate that the loss of LCMT1/decreased PP2A-C α-carboxymethylation is a major determinant of AR-addicted PCa and supports the therapeutic use of AR degraders and selective small molecule modulators of PP2A for refractory prostate cancer treatment." (PMID 37644036, 2023). "LCMT1 inhibits AR-MED1 transcriptional activity and prostate cancer growth." (PMID 37644036, 2023).
Alzheimer disease (3 papers, 2011 to 2024). A progressive, neurodegenerative disease characterized by loss of function and death of nerve cells in several areas of the brain leading to loss of cognitive function such as memory and language. "Several variants mapped to PVRL2, TOMM40, LCMT1, and RAB3GAP1 genes previously associated with Alzheimer disease." (PMID 38291454, 2024). "In humans, however, despite evidence suggesting a role for LCMT1 and PP2A in Alzheimer's disease, genetic variation of these genes did not appear to alter risk for late-onset Alzheimer's disease." (PMID 23840384, 2013).
breast carcinoma (2 papers, 2012 to 2020). "Leucine carboxyl methyltransferase (LCMT-1), a specific SAM-dependent enzyme, catalyzes the methylation of PP2A, and here, we observed that irradiation of breast cancer cells induced IR-dependent methylation of PP2A, which resulted in the catalytic activation of this phosphatase." (PMID 32764667, 2020). "Because LCMT1 is a specific SAM-dependent methyltransferase, it is tempting to speculate that an increase in the cellular SAH after the treatment of breast cancer cells with TMCG/DIPY may also result in the inhibition of PP2A assembly." (PMID 23251702, 2012).
neuroblastoma (2 papers, 2013 to 2022). Neuroblastoma (NB) is the most common solid, extracranial childhood tumor. "Increased expression of LCMT1 in neuroblastoma cells has also been shown to alter actin assembly, promoting tau-related processes and inducing neuritogenesis." (PMID 23840384, 2013). "It has been reported that LCMT1 was related to oxidative stress and was overexpressed in neuroblastoma cells, while it has not been reported in HCC yet." (PMID 36341373, 2022).
dementia with Lewy bodies (1 paper, 2021). "The study demonstrated a significant reduction in the level of LCMT-1 and a significant increase in the level of PME-1 in PD patients and dementia with Lewy bodies (DLB) patients compared to healthy controls, thereby showing decreased activity of PP2A in diseased brains." (PMID 33572534, 2021).
folate (1 paper, 2014). "Dietary folate deficiency significantly decreased LCMT1, methylated PP2A and PP2A/Bα levels in all brain regions examined from aged Mthfr+/+ mice, and further exacerbated the regional effects of MTHFR deficiency in aged Mthfr+/− mice." (PMID 25202269, 2014).
folate deficiency (1 paper, 2014). A nutritional condition produced by a deficiency of FOLIC ACID in the diet. "Comparative analysis of het mice showed that mild MTHFR deficiency further exacerbated the effects of folate deficiency on PP2Ac methylation, LCMT1 and PP2A/Bα expression levels in a brain region-specific manner." (PMID 25202269, 2014). "Of note, folate deficiency aggravated the negative effects of mild MTHFR deficiency on LCMT1 and PP2A methylation in a region-specific manner." (PMID 25202269, 2014).
hyperhomocysteinemia (1 paper, 2014). A serious metabolic condition caused by mutations in the MTHFR gene, medications, or nutritional deficiency. "We have reported in vivo that low folate status and hyperhomocysteinemia, lead to down regulation of expression levels of LCMT1, PP2A methylation, and PP2A holoenzymes containing the regulatory Bα (or PPP2R2A) subunit (PP2A/Bα)." (PMID 25202269, 2014). "Whether down regulation of LCMT1 results either from prolonged inhibition of its methyltransferase activity -due to hyperhomocysteinemia and decreased cellular methylation potential- or other regulatory mechanisms remains to be defined." (PMID 25202269, 2014).
Insulin resistance (1 paper, 2013). Increased resistance towards insulin, that is, diminished effectiveness of insulin in reducing blood glucose levels. "Lcmt1−/− animals displayed significantly decreased glucose tolerance despite higher insulin levels, a pattern often associated with insulin resistance." (PMID 23840384, 2013).
osteoporosis (1 paper, 2026). A condition of reduced bone mass, with decreased cortical thickness and a decrease in the number and size of the trabeculae of cancellous bone (but normal chemical composition), resulting in increased fracture incidence. "Na-DHA may increase osteoporosis risk by upregulating LCMT1, downregulating ARHGEF11 and VCAM1, and disrupting lipid metabolism and the balance between osteogenesis and adipogenesis, ultimately disrupting bone metabolic homeostasis." (PMID 41804343, 2026).
prostate tumor (1 paper, 2023). "Together, these findings provide evidence that LCMT1 is both a critical regulator of AR-MED1 transcriptional activity and a potent suppressor of oncogenic pathways driving prostate tumor growth in vivo." (PMID 37644036, 2023).
renal carcinoma (1 paper, 2025). A carcinoma arising from the epithelium of the renal parenchyma or the renal pelvis. "For example, MARS1 was a significant risk factor in at least 10 cancers, whereas LCMT1 and LCMT2 were protective in several tumors, especially renal cancers." (PMID 41441975, 2025).
synucleinopathy (1 paper, 2026). A neurodegenerative disease that is characterized by the abnormal accumulation of aggregates of alpha-synuclein protein in neurons, nerve fibers or glial cells. "In contrast, LCMT-1 overexpression reduced α-Syn phosphorylation and aggregation, and provided robust neuroprotection, leading to improved motor outcomes in both synucleinopathy models." (PMID 41876453, 2026).
tauopathies (1 paper, 2025). "Given the evidence implicating soluble tau oligomers in the molecular pathogenesis of tauopathies, these data suggest that targeting LCMT‐1 or PME‐1 may be viable approaches to ameliorating the impairments caused by soluble tau oligomers in these disorders." (PMID 41388803, 2025).
cancer (7 papers, 2013 to 2025). A tumor composed of atypical neoplastic, often pleomorphic cells that invade other tissues. "Nevertheless, the status of LCMT1 expression, regulation, and its role in cancer development and progression remains elusive." (PMID 37644036, 2023). "In the context of cancer, LCMT-1 and PME-1 have been shown to act as regulators of oncogenic signaling through the modulation of PP2A carboxymethylation." (PMID 36328247, 2022). "Consistently, the silence of METTL6 and LCMT1 decreased cancer cell migration, and depletion of GSTZ1 and ADH4 increased the cancer cell migration ability." (PMID 36341373, 2022). "Additionally, pan-cancer analysis in TCGA revealed a comparable level of RNA expression for LCMT1 between normal and cancer tissues across all cancer types, suggesting a potential post-translational mechanism of regulation for this enzyme." (PMID 37644036, 2023). "This replacement may circumvent the antigrowth and antiproliferative effects of methylation-sensitive PP2A heterotrimers and suggests that reduced LCMT1 activity could contribute to oncogenic transformation and cancer." (PMID 23840384, 2013). "Loss of this posttranslational modification is commonly seen in cancer; in fact, low and high protein expression levels of LCMT1 and PME1, respectively, have been identified in cancers of the lung, prostate, and liver." (PMID 41086023, 2025). "Modification of carboxymethylation, through expression changes in PME-1 or LCMT-1, is another method by which PP2A function is pathologically subverted in cancer." (PMID 36328247, 2022). "This strongly suggests a paradigm where persistent oncogenic PI3K signaling in cancer cells is achieved by the elimination of its negative regulator AB56αC and also other methylation-sensitive heterotrimers such as AB55C through S6K1-mediated degradation of LCMT1." (PMID 37644036, 2023).
tumor (4 papers, 2021 to 2025). "LCMT1 loss activates AR signaling and promotes castration-independent tumor growth." (PMID 37644036, 2023). "Next, to determine the effects of LCMT1 on tumor growth in vivo, we carried out a xenograft experiment in mice, and observed significantly reduced tumor growth in the LCMT1 overexpressing cells compared to their respective control." (PMID 37644036, 2023). "Strikingly, only LCMT1 silenced cells developed tumors in castrated mice with a tumor uptake of 83% compared to a mere 20% with the control cells." (PMID 37644036, 2023). "In addition, we explored the relationship between the TRGs risk model and TME, and revealed the strong association of METTL6, LCMT1, GSTZ1, ADH4, and ADH1A with the tumor immune infiltration and immune checkpoints." (PMID 36341373, 2022). "Multi-omics analyses revealed consistently elevated expression of AHCY, BUD23, LCMT1, MARS1, METTL6, SCLY and SEPHS1 in various tumor types." (PMID 41441975, 2025). "In this type of tumor, NNMT compromises leucine carboxyl methyl transferase 1 (LCMT1)-mediated methylation of tumor suppressor protein phosphatase 2 (PP2A) and has been identified as a negative prognostic factor." (PMID 34073600, 2021). "Finally, feedforward stabilization of LCMT1 by small molecule activator of phosphatase (SMAP) results in attenuation of AR-signaling and tumor growth inhibition in anti-androgen refractory PCa." (PMID 37644036, 2023). "We observed that ADH4, GSTZ1, and ADH1A were downregulated in HCC tumor tissues, while the LCMT1 was overexpressed in HCC tumor tissues compared with the normal tissues, which were consistent with the mRNA expression level of HCC." (PMID 36341373, 2022).
neurodegenerative disease (3 papers, 2018 to 2025). A disorder of the central nervous system characterized by gradual and progressive loss of neural tissue and neurologic function. "As an eQTL in pig brain tissue, LCMT1 is also implicated in neurodegenerative diseases such as Alzheimer's and manganese-related neurotoxicity, highlighting its importance for brain function and neuroprotection." (PMID 40969342, 2025). "In neurodegenerative diseases, NNMT reduces the catalytic ability of LCMT-1 by decreasing the concentration of SAM, leading to a decrease in the activity of LET-92/PP2A." (PMID 39035994, 2024). "More recently, LCMT-1 Tg mice showed resistance against amyloid β-protein (Aβ) injury, indicating that LCMT-1 or PME-1 can be used as a target for treatment of neurodegenerative diseases." (PMID 29950985, 2018).
LCMT1 also shares sentences with these, for which no sentence is quoted: diabetes (1 paper); metastatic prostate carcinoma (1); neurological disorders (1); prostate intraepithelial neoplasia (1).